HLA-DRB1 (major histocompatibility complex, class II, DR beta 1)
Diseases named in the same sentence as HLA-DRB1 in open-access papers (continued):
Sharing a sentence is not in itself a finding about the gene and the disease.
psoriasis (continued). "When HLA-DRB1*04 was present in patients with PsA, it occurred more frequently in those with type II psoriasis compared with patients with PsA with type I psoriasis." (PMID 17728335, 2008). "Conversely, the HLA-DRB1*07 phenotype was significantly higher in patients with PsA with type I psoriasis compared with UIA (OR 3.23, 95% CI 2.51, 4.14, p<0.0001)." (PMID 17728335, 2008). "Within patients with PsA, when the HLA-DRB1*04 phenotype was present, it occurred more commonly in patients with PsA with type II psoriasis compared with those with type I psoriasis (OR 1.81, 95% CI 1.14, 2.86, p = 0.007)." (PMID 17728335, 2008). "When compared with patients with PsA with type I psoriasis, the frequency of the HLA-DRB1*04 phenotype was significantly higher in UIA subjects (OR 2.17, 95% CI 1.66, 2.84, p<0.0001)." (PMID 17728335, 2008). "Interestingly, some alleles, particularly HLA-DRB1*15:03g and HLA-DQB1*02:02g exhibited protective effects against psoriasis in the Brazilian population, further emphasizing the complex link between genetic factors and disease susceptibility." (PMID 41512531, 2026). "There was no significant HLA-Cw and HLA-DRB1 allele difference between type I and type II psoriasis." (PMID 30650098, 2019). "In psoriasis, the role of HLA-DRB1 has also been well investigated." (PMID 27713139, 2017). "In conclusions, our results showed hypomethylation of HLA-DRB1 is associated with HLA-DRB1 mRNA expression and severity of the disease, indicating that hypomethylation of HLA-DRB1 may play roles in the pathogenesis of psoriasis." (PMID 27713139, 2017). "In order to examine whether HLA-DRB1 methylation can affect the level of HLA-DRB1 expression in psoriasis, we performed RT-PCR analysis to determine the level of HLA-DRB1 mRNA in the specimens of epidermis." (PMID 27713139, 2017). "The functional role of the HLA-DRB1 molecule in psoriasis remains enigmatic." (PMID 27713139, 2017). "Our results suggest that the primary association with HLA-C*06 and HLA-DRB1*07 is with psoriasis and not with PsA per se." (PMID 23184486, 2013). "Notably, no shared HLA risk allele has been identified (psoriasis is tied to HLA-C06:02/B27, whereas antisynthetase/DM have links to HLA-DRB1*03/*08), implying that the overlap arises from convergent inflammatory pathways rather than a common genetic cause." (PMID 40861474, 2025). "Hypomethylation of HLA-DRB1 associated with the mRNA level of HLA-DRB1 expression and severity of the disease, indicating that hypomethylation of HLA-DRB1 may also play a potential role in the pathogenesis of psoriasis." (PMID 27713139, 2017). "Similarly, there was a statistically significant association of HLA-DRB1*07 with psoriasis + PsA (OR = 2.75, Pcor < 0.0001) and a weaker association with psoriasis without PsA (OR = 2.27, Pcor = 0.002)." (PMID 23184486, 2013). "Likewise, genes located farther from HLA-C at the centromeric end, including TNF-α (tumor necrosis factor-alpha), AGER (receptor of advanced glycosylation end product-specific receptor), HLA-DRB1, HLA-DQA1 and HLA-DQB1, have also been found to be associated with psoriasis." (PMID 19680446, 2009). "The aim of this study was to compare the association between HLA-Cw*06 and HLA-DRB1, including the SE, with PsA susceptibility by comparing these phenotypes in patients with PsA, early undifferentiated inflammatory arthritis (UIA) alone, psoriasis alone and healthy controls." (PMID 17728335, 2008). "Replication of effect of HLA-DRB1 residues 9 and 71 on development of ADA in individuals with psoriasis sampled within 6 months of treatment initiation." (PMID 36810251, 2023). "These may provide insight into whether the observed association with HLA-DRB1 and ADA against adalimumab also predicts the development of ADA against adalimumab in other disease settings and the development of ADA against other systemic medications for the treatment of psoriasis." (PMID 36810251, 2023).
Graves disease (18 papers, 2009 to 2025). Graves' disease is an autoimmune disorder that leads to overactivity of the thyroid gland (hyperthyroidism).It is caused by an abnormal immune system response that causes the thyroid gland to produce too much thyroid hormones. "HLADRB1*03 allele is associated with young age at diagnosis of Graves' disease in polish population." (PMID 23544060, 2013). "This might be the first report to associate HLA-DRB1*11:02:01 as a possible risk allele in PD, although it has been associated with systemic juvenile idiopathic arthritis, Graves’ disease and MS." (PMID 38590523, 2024). "Another example of associations with the HLA system is a case report suggesting that the HLA-DRB1*03 allele may explain a common etiology underlying the comorbidity of Graves’ disease, type 2 diabetes, and schizophrenia in one patient." (PMID 36231907, 2022). "Polymorphism of HLADRB1*03 is associated with early age at diagnosis of Graves' disease." (PMID 23544060, 2013). "Therefore, a further study involving HLA-DR genotyping of the Polish controls, as well as adequately powered replication studies in other Caucasian populations are required to determine the independent role of IKBL SNPs and HLADRB1*03 alleles in pathogenesis of Graves' disease." (PMID 19886988, 2009). "We report two patients with Grave’s disease (GD), carrying the HLA-DRB1 04:06 genotype, who experienced hypoglycemic episodes after taking methimazole." (PMID 37587407, 2023). "Graves’ disease (GD) is an organ-specific autoimmune thyroid disorder characterized by anti–thyrotropin receptor (TSH-R) antibodies (TRAb), with strong genetic susceptibility conferred by the HLA-DRB1*03:01 (DR3) allele." (PMID 41256857, 2025). "In a recent case reports study, HLA-DRB1*11:01 was speculated to be involved in the pathogenesis of Graves’ disease following SARS-CoV-2 vaccination." (PMID 37845715, 2023). "HLA-DRB1-03 genotypes in patients with Graves' disease (GD) stratified by the age at GD diagnosis." (PMID 23544060, 2013). "We evaluated the associations of genetic variants at the HLA-B and HLA-DRB1 loci and 32 candidate single nucleotide polymorphisms (SNPs) with agranulocytosis in 29 patients with ATD-induced agranulocytosis and in 140 patients with Graves’ disease (GD) as controls." (PMID 28931918, 2017). "The frequency of thyroid diseases, such as Graves’ disease and Hashimoto thyroiditis, increased in HLA-DRB1*04:10-positive MMD patients compared with that in HLA-DRB1*04:10-negative MMD patients." (PMID 31412073, 2019). "The results indicated that the frequency of thyroid diseases, including Graves’ disease (GD) and Hashimoto thyroiditis (HT), is high in HLA-DRB1*04:10-positive MMD patients compared with that in HLA-DRB1*04:10-negative MMD patients (frequency 23.1% vs. 4.1% in the control group; P = 0.029)." (PMID 31412073, 2019).
uveitis (17 papers, 2013 to 2025). An inflammatory process affecting a part of or the entire uvea. "This association correlated strongly with that of HLA‐DRB1 position 13 (P = 2.2 × 10−34), where the amino acids serine (OR 1.6, 95% CI 1.4–1.9) and glycine (OR 1.9, 95% CI 1.5–2.3) conferred the most risk of uveitis." (PMID 39030878, 2024). "In ICIU, HLA-DRB1*04:05 was associated with the pathogenesis of VKH-like uveitis, suggesting that ICI-associated VKH-like uveitis has a similar pathogenesis to VKH." (PMID 37604934, 2023). "In one study, 100% of patients with VKH-associated uveitis who underwent HLA typing were found to have HLA-DRB1*04:05." (PMID 38264654, 2023). "HLA-DRB1*04/*15 increased the risk of extrapulmonary involvement (including uveitis) in the European population." (PMID 33912164, 2021). "We previously reported an association of HLA-A*02:06 with JIA accompanied by uveitis and of HLA-DRB1*04:05 with polyarticular JIA." (PMID 28182665, 2017). "Other HLA alleles have also been reported to be associated with JIA-associated uveitis such as HLA-DRw5, HLA-DRB1*1104, HLA-DRB1*1301." (PMID 24658012, 2014). "Additionally, HLA-DRB1*0103 and HLA-B*44 are associated with extraintestinal manifestations like arthritis and uveitis." (PMID 40806407, 2025). "Association testing of all genetic markers in the cohort identified amino acid position 11 of HLA‐DRB1 (P = 1.6 × 10−35) as the most significantly associated marker, where serine was associated with increased risk of uveitis (OR 2.2, 95% confidence interval [95%] CI 1.9–2.5)." (PMID 39030878, 2024). "Regarding extraintestinal manifestations, HLA-DRB1*01:03 shows the strongest association with type I arthritis and uveitis, while HLA-B44 and TNF-1031C are linked to type II arthritis and erythema nodosum, though these associations may partly reflect colonic disease involvement." (PMID 40806407, 2025). "The specific alleles HLA-DRB1*1501 and HLA-DRB1*1503, which confer the greatest predisposition to MS, have also been linked to an increased incidence of infections suspected to have a fungal etiology, such as pulmonary sarcoidosis, uveitis, or allergic bronchopulmonary aspergillosis." (PMID 40791596, 2025). "In a cohort of Japanese patients, HLA-DRB1*04 was linked to polyarticular JIA, while HLA-DRB1*02 was associated with more complex forms of JIA-associated uveitis." (PMID 39484788, 2025). "VKH-like uveitis is often associated with the Japanese population, which has a higher incidence of HLA-DR4 and HLA-DRB1." (PMID 38337852, 2024). "Case reports described links between ICI-induced VKH disease-like uveitis and HLA-DRB1*04:05 and/or HLA-DRB1*04:10." (PMID 38337852, 2024). "We also report that serine at position 11 of HLA‐DRB1 is correlated with uveitis in patients with JIA." (PMID 39030878, 2024). "Haasnoot et al3 reported that the presence of serine at position 11 of HLA‐DRB1 is correlated with JIAU, and Heiligenhaus et al27 reported that the position 11 of HLA‐DRB1 is a good predictor of uveitis in patients with JIA." (PMID 39030878, 2024). "In terms of patient HLA types, 100% of patients with VKH-like uveitis who underwent HLA typing were positive for HLA-DRB1*04:05, which has also been observed in several reports of VKH-like ICIU12,13,22–24." (PMID 37604934, 2023). "Three patients developed Harada-like uveitis, two of whom tested positive for HLA-DRB1*0405 and DR04 and 07 suballeles." (PMID 37897028, 2023). "Four patients with VKH-like uveitis underwent HLA genotyping and were all positive for HLA-DRB1*04:05." (PMID 37604934, 2023). "Additionally, incorporation of the genetic risk factors serine at position 11 of HLA‐DRB1, rs2523765, and HLA‐DPB1*0201 to this model found that genetic risk factors significantly improve the fit of the statistical model for uveitis." (PMID 39030878, 2024).
uveitis (continued). "This is also supported by our previous finding in this same study population showing that none of the patients had the HLA-DRB1*15 genotype, which has been suggested to be associated with increased risk for uveitis and is relatively common in the Finnish population (15%)." (PMID 30779760, 2019). "This demonstrates that the magnitude of effect for serine at position 11 of HLA‐DRB1 is consistent between all subtypes of JIA and oligoarthritis and suggests that individuals with this ILAR subtype may carry genetic risk factors that place them at a higher risk for uveitis." (PMID 39030878, 2024). "The frequency of HLA-C*01, HLA-DRB1 *04:05, and HLA-DQB1*04:01 was significantly higher in cases with VKH-like uveitis (P = 0.029)." (PMID 37604934, 2023). "In conclusion, we have shown that the presence of HLA-DRB1*04 may affect post-treatment visual outcomes and CCT in unclassifiable uveitis patients." (PMID 34963463, 2021). "All 3 patients with non-VKH-like uveitis were negative for HLA-DRB1*04:05." (PMID 37604934, 2023).
viral infections (17 papers, 2010 to 2025). "In fact, the presence of ≥ 3 mismatches in HLA class I was associated with a significantly higher viral infection incidence after being adjusted by HLA-DRB1 mismatch and other confounding factors (HR 2.38 [1.09–5.17], p = 0.02)." (PMID 33273656, 2020). "In humans, specific alleles of the HLA-DPA1, HLA-DQA1 and HLA-DRB1 loci have been associated with viral infections." (PMID 27812212, 2016). "Samples from AHUE cases have shown positivity for the HLA-DRB1*04:01 allele, suggesting that viral infections, like HAdV or AAV2, may activate a T helper cell-mediated pathological response in genetically susceptible hosts, leading to AHUE." (PMID 38089685, 2023). "Moreover they stated that HLADRB1*13 has been implicated in the clearance of viral infection and in the immune response against viral proteins." (PMID 21067577, 2010). "Although the exact cause of MS is yet unknown, viral infections such as EBV, environmental factors, and autoimmune and genetic mechanisms involving HLA-DRB1 loci are implicated." (PMID 34603807, 2021). "In Class1, the viral infection pathways (e.g., HSV-1, EBV) and antigen presentation (e.g., HLA-DRB1/DQB1/C, CD74, CTLA4, GZMB, PRF1) were primarily enriched." (PMID 41394852, 2025). "We have shown that HLA-DRB1*0101 Ifnar1−/− mice, mount an antigen-specific CD4+ T cell response against SARS-CoV-2 after DNA vaccination or viral infection, and a CD4+ T cell response to OC43 that cross-reacts with SARS-CoV-2." (PMID 38278784, 2024). "They considered HLA-DRB1 and -DQB1 as crucial genetic factors governing host vulnerability to viral infections." (PMID 36743382, 2023).
autoimmune hepatitis (16 papers, 2010 to 2026). Hepatitis caused by autoantibodies. "The aim of this study was to determine the frequency of HLA-DRB1 in patients with autoimmune hepatitis as a risk factor for occurrence, its relation to preceded HAV infection, and treatment outcome." (PMID 21067577, 2010). "The aim of this study was to determine the frequency of HLA-DRB1 in children with autoimmune hepatitis (AIH) as a risk factor for occurrence, its relation to preceding hepatitis A infection and treatment outcome." (PMID 21067577, 2010). "It was concluded from this study that HLA-DRB1*13 may be a susceptibility allele for the occurrence of autoimmune hepatitis in our population." (PMID 21067577, 2010). "It is concluded from the previous study that HLA-DRB1*13 may be a susceptibility allele for the occurrence of autoimmune hepatitis in our population." (PMID 21067577, 2010). "The human leukocyte antigen (HLA) type has been suggested to affect hepatitis susceptibility via immune-modifying effects in hosts, and HLA-DRB1 04:01 has been reported as a host factor responsible for autoimmune hepatitis (AIH) in adults." (PMID 40079016, 2025). "In this regard, it should be noted that the HLA-DRB1*03:01 allele, which was relatively common in our study cohort (MAF = 0.159), has been reported to be a risk allele for autoimmune hepatitis (AIH)." (PMID 36003377, 2022). "HLA-DRB1*04/DRB1*08 heterozygous genotype frequencies are also increased in autoimmune hepatitis, another organ-specific autoimmune disease." (PMID 35705662, 2022). "In addition, PBC patients carrying HLA-DRB1*15:01:01 and HLA-DQA1*03:03:01 would have a higher predisposition toward developing concomitant autoimmune hepatitis (AIH)." (PMID 37325616, 2023).
Löfgren’s syndrome (16 papers, 2010 to 2025). "Another SNP near HLA-DQA1 (rs2187668) is significantly associated with Lofgren’s syndrome and HLA-DRB1*04:01 with ocular sarcoidosis in EDs." (PMID 38390497, 2023). "An acute, but resolving expression of the disease, so-called Lofgren syndrome, appears more frequently with the HLA-DRB1*03 and DQB1*0201 alleles." (PMID 32823753, 2020). "Most classical examples being strong association found between HLA-DRB1*03 and Löfgren’s syndrome in caucasian populations, whereas among the Japanese, this association is absent due the lack of HLA-DRB1*03 allele in the population." (PMID 28469621, 2017). "Previous reports have shown especially a strong association between HLA-DRB1*03 and Löfgren's syndrome, and a good prognosis." (PMID 20187937, 2010). "HLA-DRB1*03 strongly associated with Löfgren's syndrome (OR 6.71, p = 2 × 10-24), and especially with a resolving form of the disease (OR 11.42, p = 8 × 10-27)." (PMID 20187937, 2010). "Thus, the HLA-DRB1*0301 gene is associated with Löfgren’s syndrome and the resolution of the disease." (PMID 39598118, 2024). "In Swedish patients, HLA-DRB1*04 is associated with extra pulmonary manifestations, HLA-DRB1*03 with Löfgren’s syndrome and resolving disease, while HLA-DRB1*15 is more frequent in patients with a chronic disease course." (PMID 37161980, 2023). "HLA-B*08:01, HLA-C*07:01, HLA-DRB1*03:01, HLA-DQA1*05:01, and HLA-DQB1*02:01 variants associated with Löfgren’s syndrome, a more benign phenotype." (PMID 37153085, 2023). "The majority of Löfgren's syndrome patients express HLA-DRB1*03:01, with most of these patients resolving their disease within 2 years." (PMID 32256501, 2020). "The majority of Löfgren's syndrome patients in Sweden express HLA-DRB1*03:01 (HLA-DR3), and expression of HLA-DR3 was strongly associated with disease resolution and an excellent prognosis." (PMID 32256501, 2020). "For example, the HLA-DRB1*03 and DQB1*0201 alleles have been associated with an acute disease onset, Löfgren syndrome and resolving disease, whereas in contrast HLA-DRB1*15 and DQB1*0601 are associated with chronic sarcoidosis." (PMID 24339826, 2013). "In the present study we therefore sub-grouped our patients into those with Löfgren's syndrome (LS), and those without Löfgren's syndrome (non-LS), and analysed any correlations between distinct HLA-DRB1 alleles and the risk for disease as well as the disease course." (PMID 20187937, 2010). "Interestingly, associations between HLA-DRB1 alleles and disease were in several cases clearly different in the two patient sub-groups; while DRB1*01 strongly protected against disease in non-Löfgren's patients, we found no influence on Löfgren's syndrome." (PMID 20187937, 2010).